ENSG00000288671 (novel protein)
Gene: Protein-coding gene on chromosome 19 (42,215,133 to 42,232,149, reverse strand). Ensembl gene ENSG00000288671.
Genetic constraint (gnomAD): Loss-of-function variants: 4 observed, 5.09 expected, observed/expected ratio (o/e) 0.79, 90% interval 0.38 to 1.67. That is too few expected variants to judge how well the gene tolerates losing a copy. Missense variants: 52 observed, 57.02 expected, observed/expected ratio (o/e) 0.91, 90% interval 0.73 to 1.15. Synonymous variants: 19 observed, 17.7 expected, observed/expected ratio (o/e) 1.07, 90% interval 0.75 to 1.57.